PRCC (proline rich mitotic checkpoint control factor)
Description:
May regulate cell cycle progression through interaction with MAD2L2.
Synonyms: TPRC; RCCP1
Tractability: PROTAC: ubiquitination databases record sites on it; its protein half-life has been measured.
Gene: Protein-coding gene on chromosome 1 (156,750,610 to 156,800,817, forward strand). Ensembl gene ENSG00000143294.
Subcellular location: Nucleus
Subcellular location (Human Protein Atlas): Nuclear speckles
Pathways (Reactome):
Disease: Dengue Virus-Host Interactions
Metabolism of RNA: mRNA Splicing - Major Pathway
Gene Ontology:
Molecular function: protein binding
Biological process: regulation of cell cycle
Cellular component: nuclear speck; nucleus; nucleoplasm
Genetic constraint (gnomAD): Loss-of-function variants: 10 observed, 42.07 expected, observed/expected ratio (o/e) 0.24, 90% interval 0.15 to 0.4. The upper end of that interval is the gene's LOEUF score, 0.4, which puts it in group 1 of 6, group 1 being the genes least tolerant of losing a copy. Missense variants: 573 observed, 603.41 expected, observed/expected ratio (o/e) 0.95, 90% interval 0.89 to 1.02. Synonymous variants: 278 observed, 253.23 expected, observed/expected ratio (o/e) 1.1, 90% interval 1 to 1.21.
Homologues: Orthologues: chimpanzee PRCC (100% identical), pig PRCC (98% identical), dog PRCC (95% identical), macaque PRCC (95% identical), mouse Prcc (93% identical), rat Prcc (93% identical), rabbit PRCC (88% identical), tropical clawed frog prcc (63% identical), guinea pig PRCC (60% identical), zebrafish prcc (42% identical), Drosophila melanogaster CG17249 (23% identical), Caenorhabditis elegans prcc-1 (20% identical).
Diseases named in the same sentence as PRCC in open-access papers:
PRCC is named in the same sentence as 48 diseases in open-access papers, as found by Europe PMC text mining. Sharing a sentence is not in itself a finding about the gene and the disease. The quoted sentences say what the papers report.
renal cell carcinoma (15 papers, 2009 to 2024). "Previously, we identified MAD2B as an interactor of the renal cell carcinoma (RCC)-associated protein PRCC." (PMID 21152103, 2010). "Previously, we identified the mitotic arrest deficient protein MAD2B (MAD2L2) as a bona fide interactor of the renal cell carcinoma (RCC)-associated protein PRCC." (PMID 19753112, 2009). "PRCC encodes proline-rich protein PRCC (ppPRCC), a protein of unknown function associated with renal cell carcinomas." (PMID 28352227, 2017). "In patients with renal cell carcinoma, PRCC has been repeatedly found as part of oncogenic fusions, with the N-terminal proline-rich region of the PRCC gene fused to one of several transcription factor genes." (PMID 35143478, 2022). "It is indeed recognized that pRCC displays a morphological pattern shared by several different types of renal cell carcinomas." (PMID 34482820, 2021). "The three most common Xp11 translocation renal cell carcinomas are those bearing the t(X;1) (p11.2;q21) which fuses the PRCC and TFE3 genes, the t(X;17) (p11.2;q25) which fuses the ASPL and TFE3 genes, and the t(X;1) (p11.2;p34) which fuses the SFPQ (PSF) and TFE3 genes." (PMID 31382581, 2019). "Furthermore, we confirmed that PFK-015 and sunitinib could highly synergistically suppress pRCC cell proliferation, which may provide a promising new treatment strategy for advanced renal cell carcinoma making this combination drug therapy." (PMID 38622715, 2024). "Notably, these predictions are renal cell carcinoma-specific, especially for pRCC." (PMID 35013217, 2022). "In the nineties, among Xp11 renal cell carcinoma, ASPL, PRCC, and SFPQ (PSF) were the first genes recognized as partners in TFE3 rearrangement." (PMID 31382581, 2019).
kidney cancer (7 papers, 2019 to 2025). Primary or metastatic malignant neoplasm involving the kidney. "c-met-mutated PRCC represents a major form of hereditary kidney cancer among kidney cancers which are the seventh most common malignancies in the United States." (PMID 31575031, 2019). "To further investigate the influence of antihypertensive drugs on the risk of different histological types of kidney cancer, we performed two-sample MR to study the effect of genetically proxied therapeutic inhibition for antihypertensive drug targets on the risk of ccRCC, pRCC, and chRCC." (PMID 40535814, 2025). "HNF1β, a candidate pRCC master TF, has been shown to be expressed in the embryonic kidney and in pRCC, and it is upregulated in pRCC compared to other kidney cancer histologies." (PMID 36681680, 2023). "pRCC is an heterogenous subtype of kidney cancer, characterized by the common feature of papillae formation." (PMID 33233657, 2020). "Herein, we fully characterize the whole genome and DNA methylation of pRCC and rarer kidney cancer subtypes, specifically examining both the core and periphery of selected tumors and, when available, metastatic lesions in order to investigate ITH and clonal evolution." (PMID 32555180, 2020). "pRCC is the second most common subtype of renal malignant tumors." (PMID 33139776, 2020). "Due to the low number of samples of pRCC and chRCC, we could not get a clear indication of the differences between histological kidney cancer types, and they were therefore excluded from the analysis with TKIs." (PMID 36093296, 2022). "This is the case of kidney cancers, where transitory activation of the NRF2 signature protects the kidney epithelium from carcinogens and chemotherapies such as cisplatin, while its hyperactivation in ccRCC and PRCC is crucial in supporting a malignant phenotype and chemoresistance." (PMID 33233657, 2020).
oncocytoma (6 papers, 2013 to 2024). "UQCRFS1 expression was somewhat lower in pRCC (mean expression level: 0.83; p=0.004), but similar in chRCC (1.40; p=0.364) and oncocytoma (0.85; p=0.0176)." (PMID 27845902, 2016). "Interestingly, we and others have seen pRCC in the context of “collision tumors” present in the same lesion together with other RCCs or even oncocytomas." (PMID 34680535, 2021). "We found that, after contrast administration, oncocytoma had the highest enhancement change, and among the subtypes of RCC, ccRCC displays the highest enhancement, whereas chrRCC enhances moderately and pRCC enhances the least." (PMID 33126571, 2020). "Among RCTs, intense staining was shown by ccRCC, oncocytomas, and pRCC, whereas most chrRCC were negative." (PMID 23890189, 2013). "Likewise, miRNA-210-3p is upregulated in ccRCC and pRCC, with no change in oncocytoma." (PMID 33535553, 2021).
papillary renal cell carcinoma (6 papers, 2017 to 2024). A rare subtype of renal cell carcinoma, arising from the renal tubular epithelium and showing a papillary growth pattern, which typically manifests with hematuria, flank pain, palpable abdominal mass or nonspecific symptoms, such as fatigue, weight loss or fever. "That was the case for BRCA1, ERBB2 and ERBB3 loci that were found to be deregulated in triple-negative breast cancers or von Hippel-Lindau (VHL) tumour suppressor gene and PRCC that was linked to clear cell renal cell carcinoma and papillary renal cell carcinoma respectively." (PMID 31105870, 2019). "PRCC encodes proline-rich protein PRCC (ppPRCC) of unknown function associated with papillary renal cell carcinoma." (PMID 28352227, 2017). "For prostate cancer and PRCC (papillary renal cell carcinoma), MFG-E8 expression was higher in malignant areas compared to nonmalignant areas." (PMID 35681775, 2022). "This identification of specific biological functions that may be involved in the mechanism of pRCC development provides new clues and directions for efforts to develop future treatments for papillary renal cell carcinoma." (PMID 36785669, 2023).
breast carcinoma (3 papers, 2013 to 2024). "According to the latest studies, the expression of C1QB was upregulated in CCRCC patients, glioma patients, gastric cancer patients, CRC patients, PRCC, and breast cancer." (PMID 39109334, 2024).
colorectal cancer (2 papers, 2016 to 2023). A primary or metastatic malignant neoplasm that affects the colon or rectum. "In another study, lncRNA CKMT2-AS1 depressed the growth of colorectal cancer cells by targeting the AKT/mTOR pathway, which contradicts our data that lncRNA CKMT2-AS1 could be a poor indicator for pRCC rather than a protective factor." (PMID 36674979, 2023).
renal carcinoma (2 papers, 2023 to 2026). A carcinoma arising from the epithelium of the renal parenchyma or the renal pelvis. "This broad inclusion of renal cancer subtypes was essential for capturing the full spectrum of molecular variation across these tumors, enabling us to identify genes consistently dysregulated in pRCC while distinguishing them from other renal malignancies." (PMID 41540036, 2026).
benign renal tumors (1 paper, 2025). "Our findings demonstrate a distinct overexpression of TROP-2 at both the mRNA and protein levels in pRCC, with limited expression in other RCC subtypes and benign renal tumors." (PMID 40888912, 2025).
eosinophilia (1 paper, 2024). "In this case of FH-deficient pRCC, a heavily pre-treated patient who responded remarkably to late nivolumab rechallenge accompanied by eosinophilia illustrates the potential of immunotherapy in managing such aggressive malignancies." (PMID 39496729, 2024).
hepatocellular carcinoma (1 paper, 2021). A malignant tumor that arises from hepatocytes. "This study aims to elucidate PRCC molecular function, regulatory mechanism and diagnostic value in hepatocellular carcinoma (HCC)." (PMID 34715922, 2021).
Huntington disease (1 paper, 2021). Huntington disease (HD) is a rare neurodegenerative disorder of the central nervous system characterized by unwanted choreatic movements, behavioral and psychiatric disturbances and dementia. "KEGG pathway enrichment analysis manifested the physiological characteristics of these genes, including Huntington disease, citrate cycle and substance metabolism for ccRCC, and oxidative phosphorylation, citrate cycle, substance metabolism and Huntington disease for pRCC." (PMID 34193180, 2021).
kidney chromophobe carcinoma (1 paper, 2024). "For instance, unlike pRCC and ccRCC originating from proximal tubular cells with high MAEL expression, kidney chromophobe carcinoma (KICH) develops from distal tubular cells that did not express MAEL and had far lower expression of MAEL than KIRC and KIRP." (PMID 38301040, 2024).
kidney stones (1 paper, 2019). "Moreover, an increased pRCC risk, but not ccRCC risk, was observed in relation to a history of kidney stones." (PMID 30563989, 2019).
lung carcinoma (1 paper, 2025). "The PRCC gene has been implicated in signaling cascades that may contribute to tumorigenesis in lung cancer." (PMID 41144480, 2025).
lymph node metastasis (1 paper, 2023). "Collectively, based on our findings, HMGA2 expression appears to be correlated with PRCC tissue subtypes, cell pleomorphisms, and significantly associated with clinical stage and lymph node metastasis." (PMID 37283291, 2023).
melanoma (1 paper, 2019). A malignant, usually aggressive tumor composed of atypical, neoplastic melanocytes. "In contrast to melanoma and pRCC, these samples were highly heterogeneous, typically more difficult to dissect from surrounding healthy tissues and in some cases heavily infiltrated with mucinous areas (data not shown)." (PMID 30718808, 2019).
mesothelioma (1 paper, 2022). A usually malignant and aggressive neoplasm of the mesothelium which is often associated with exposure to asbestos. "High expression levels of TCOF1 were related to poor prognosis for overall survival (OS) in kidney chromophobe (KICH; P = 0.014), PRCC (P = 0.0027), LIHC (P = 0.0037), and mesothelioma (MESO, P = 0.0091) in TCGA datasets." (PMID 35093935, 2022).
metastatic tumor (1 paper, 2022). "We observed heterogeneity in allele frequencies of these variants with some being highly clonal-specific, e.g., 7207G>A was mostly specific to PDX pRCC alone and not found in the metastatic tumor populations." (PMID 35260582, 2022).
oncocytic tumors (1 paper, 2021). "Some oncocytic tumors are difficult to separate from papillary RCC, because oncocytic cytoplasmic changes can be seen in pRCC, translocation RCC and FH-deficient RCC." (PMID 34680535, 2021).
renal tumors (1 paper, 2024). "AMACR (P504S), as a specific and sensitive marker of PRCC, is also highly expressed in OPRCC, while its expression is relatively small and weak in the immunohistochemistry of other renal tumors." (PMID 39957804, 2024).
Right ventricular cardiomyopathy (1 paper, 2020). Right ventricular dysfunction (global or regional) with functional and morphological right ventricular abnormalities, with or without left ventricular disease. "Particularly, for PRCC, the spliceosome pathway was upregulated, and vascular smooth muscle contraction and arrhythmogenic right ventricular cardiomyopathy were downregulated." (PMID 33371886, 2020).
tumor (49 papers, 2007 to 2026). "Xenograft models for NF2-deficient PRCC also demonstrated reduced tumor growth in response to dasatinib." (PMID 29535838, 2018). "Loss of 3p in pRCC was associated with worse prognosis such as higher T stage and grade, lymph node involvement, distant metastasis, larger tumour size, and worse survival." (PMID 26448938, 2015). "Taken together, these results robustly established the tumor-associated role of HNRNPC in pRCC." (PMID 35502201, 2022). "In this first whole genome study of pRCC, we found several novel noncoding alterations that might drive tumor development and we explored the mutational landscape and evolutionary trees to better understand tumor heterogeneity." (PMID 28358873, 2017). "Discordant SSNVs in mRCC and pRCC might result from the gradual increase in point mutations and clonal selection with tumor evolution, as previously reported." (PMID 27139883, 2016). "However, these mutations were found in only 10% to 15% of pRCC tumours in these studies." (PMID 35037540, 2022). "The heterogeneity of pRCC, especially in type II tumors, is increasingly understood to reflect different stages of tumor progression." (PMID 41540036, 2026). "In conclusion, pRCC is characterised by aberration in the NRF2‐ARE pathway in a subset of aggressive tumours." (PMID 39707614, 2025). "The potential of these tumor antigens for the development of an anti-PRCC mRNA vaccine has been proposed." (PMID 36836593, 2023). "The purpose of this study was to identify potential tumor antigens and robust immune subtypes for the development and appropriate use of anti-PRCC mRNA vaccines, respectively." (PMID 36836593, 2023). "In the quest for potential tumor antigens of PRCC, the abnormally over-accumulated genes were interrogated and a total of 1014 up-regulated genes were screened out, which held the likelihood of encoding TAAs." (PMID 36836593, 2023). "In a study on the comprehensive molecular characterization of PRCC, alteration of the MET gene (mutation, splice variant, or gene fusion) or gain of chromosome 7 copy number was identified in 81.3% of Type 1 tumor." (PMID 37283291, 2023). "Our findings supported a different potential involvement of CBX6 in ccRCC and pRCC, and a similar tumor suppressive role for CBX7 in both assessed RCC subtypes." (PMID 36292141, 2022). "Since HNRNPC was reported to regulate cancer progression through diverse systems, the specific mechanisms of its tumor-promoting role in pRCC came as an unavoidable concern." (PMID 35502201, 2022). "Data validation in tissue samples confirmed that levels of CAMK2B and GUSBP11 were lower, while those of miR-432-5p were higher in tumor tissue than in paired tumor-adjacent tissue, suggesting a protective role of the axis in pRCC." (PMID 35626699, 2022). "In order to study the interaction between pRCC tumor and myeloid cells, we established primary cultures from pRCC tissue." (PMID 28759013, 2017). "PRCC is associated with activation of the MET pathway in a subset of tumors, resulting in a cascade of intracellular signaling leading to tumor cell growth, angiogenesis, migration and invasion." (PMID 24568263, 2014). "In terms of immunohistochemistry, GAP was strongly expressed in the membrane of proximal tubule cells, whereas tumours from this origin showed only a mild membrane positivity (CCRCC) or even very weak staining (PRCC)." (PMID 24885240, 2014). "All the results confirmed that KHSRP as the oncogene, participated in the pRCC tumor progression." (PMID 39439895, 2024). "Importantly, we found that the expression is retained in a majority of CCRCC and PRCC cases, as assessed by immunohistochemistry combined with bioinformatical analysis of tumor mRNA levels for these genes deposited in the TCGA data sets." (PMID 36595529, 2023). "In addition, there were notable differences in PanCK, a marker of tumor cells, with a significantly increased population in pRCC compared with that in ccRCC." (PMID 37638025, 2023).